LEP (leptin)
Diseases named in the same sentence as LEP in open-access papers (continued):
Sharing a sentence is not in itself a finding about the gene and the disease.
metabolic syndrome (continued). "Some spontaneous mutation models such as ob/ob and db/db mice have also been successful models to feature leptin deficiency and/or defective leptin binding and leading to obesity, dyslipidemia and other related commodities." (PMID 35252310, 2022). "The leptin-adiponectin ratio (LAR) has been confirmed to be a better diagnostic marker for metabolic syndrome than either hormone on its own, that is elevated leptin levels or decreased adiponectin levels." (PMID 35628271, 2022). "Some studies described differential effects of Zn between men and women, such as in serum leptin levels with Zn supplementation, association with metabolic syndrome, and prevalence of kidney stones." (PMID 34629117, 2021). "Gut bacteria of leptin-deficient transgenic mice with metabolic syndrome have been reported to show enrichment of ascorbate and aldarate metabolism." (PMID 33658065, 2021). "Leptin administration therapy with metreleptin, a recombinant human leptin analogue, has been approved for the treatment of the metabolic abnormalities linked to dyslipidemia." (PMID 34233759, 2021). "Seven-week-old male control (B6.V-Lep ob/+JRj) and leptin-deficient (metabolic syndrome) (B6.V-Lep ob/obJRj) mice were used in the study." (PMID 33467410, 2021). "Focusing on non-psychiatric patients with metabolic disturbances, numerous clinical studies have shown that dysregulated leptin and adiponectin levels are strongly associated with dyslipidemia." (PMID 34122163, 2021). "Still, at least to our knowledge, no polymorphisms in the gene encoding LEPR has been linked to psoriasis so far, while in the case of the gene encoding leptin, rs7799039 was associated with the plasma leptin levels and the metabolic syndrome with psoriasis." (PMID 34685457, 2021). "Previous studies have indicated that several adipokines including leptin, visfatin, fetuin-A, and adiponectin are strongly associated with the development of obesity, type 2 diabetes, metabolic syndrome (MetS) and NAFLD." (PMID 33743586, 2021). "Further, LGS reduced the frequency of metabolic syndrome (MeS) components along with deceased hsCRP associated with the improvement of leptin/adiponectin ratio." (PMID 33981153, 2021). "The presence of metabolic syndrome appears to significantly modulate the beneficial effects associated with leptin." (PMID 34679472, 2021). "Higher proportion of subcutaneous fat in females makes them more resistant to pathologies associated with the metabolic syndrome than males, as it produces leptin and adiponectin; estradiol stimulates while testosterone inhibits leptin expression." (PMID 34745011, 2021). "Excretion of UA is inversely associated with leptin as a predictive marker for metabolic syndrome secreted by adipose tissue." (PMID 34335246, 2021). "Third, genetic polymorphisms of 5-HT2C, leptin and leptin receptor have been proven to influence weight gain and metabolic syndrome during clozapine treatment; however, these pharmacogenetic parameters were not investigated in this study." (PMID 33277605, 2020). "Even in NAFLD cases associated with metabolic syndrome, the involvement of glucocorticoids, GH, thyroid hormones, and a loss of appetite control, i.e., so-called leptin resistance, should be considered." (PMID 33102399, 2020). "The intestinal barrier dysfunction under aberrant leptin signaling has been associated with the hyperglycemic state characteristic of the metabolic syndrome and related diseases." (PMID 33316927, 2020). "Central leptin signaling can lower hyperglycemia in insulin-deficient rodents via multiple mechanisms, including improvements of dyslipidemia." (PMID 33071988, 2020). "The excessive fat accumulation in the liver is strongly associated with multifactorial risk factors such as obesity, leptin and insulin resistance (IR), dyslipidemia and metabolic syndrome." (PMID 31936799, 2020).
metabolic syndrome (continued). "The elevated leptin plasma concentration was associated with metabolic syndrome regardless previous demographic studies." (PMID 31462242, 2019). "For instance, higher serum leptin concentrations are known to accompany increased BMI and metabolic syndrome, which expose individuals to greater cerebrovascular risk." (PMID 30893833, 2019). "Adipokines like leptin, adiponectin, visfatin, and resistin have been identified as potential mediators of metabolic syndrome and associated with insulin resistance, central obesity, dyslipidemia, and hypertension in autoimmune disease." (PMID 30712132, 2019). "Leptin, an adipocytokine produced by adipose tissue, is associated with dyslipidemia, and recent study has demonstrated that leptin contributes to hypertension through upregulation of central renin–angiotensin system and proinflammatory cytokines." (PMID 29338791, 2018). "In MS patients also developing metabolic syndrome, pioglitazone treatment decreases leptin and increases adiponectin serum levels in association with reduced secretion of pro-inflammatory cytokines by PBMC." (PMID 29865151, 2018). "The adiponectin/leptin ratio is associated as a better inflammatory biomarker of inflammation in metabolic syndrome patients than these adipokines analyzed in isolation." (PMID 29791651, 2018). "Even though the therapeutic potential of inhibition of leptin action in disease conditions associated with metabolic syndromes is well recognized, inhibition of leptin signaling pathway/s in breast cancer has not been adequately investigated." (PMID 28930270, 2017). "Some others studies found this marker to be a better tool for the diagnosis of metabolic syndrome and risk stratification of subjects, than adiponectin or leptin alone." (PMID 28878827, 2017). "In this study higher levels of LAR have been found to be significantly associated with metabolic syndrome as well as higher levels of leptin and lowered ones of adiponectin." (PMID 28878827, 2017). "Data on these metabolic markers are scare in Africa and this study aimed to assess the association between the leptin-to-adiponectin ratio (LAR) with metabolic syndrome in a Cameroonian population." (PMID 28878827, 2017). "Binary logistic regression analysis metabolic syndrome was significantly associated with higher levels of leptin (OR = 1.42, p value =0.003) as well as with lower levels of adiponectin (OR = 0.46, p value =0.001) and LAR (OR = 1.5, p value <0.0001)." (PMID 28878827, 2017). "In patients with psoriasis, increased leptin expression has been shown to be associated with the metabolic syndrome." (PMID 29065479, 2017). "Serum leptin and proinflammatory cytokines have been associated in the development of several age-associated conditions such as metabolic syndrome and atherosclerosis." (PMID 26473487, 2015). "Plasma leptin levels are closely associated with adiposity, and its level correlated with increased metabolic syndrome components." (PMID 26338087, 2015). "In this study, leptin was found as the most sensitive adipokine marker for predicting the accumulation of cardiovascular risk factors and the presence of metabolic syndrome." (PMID 26581745, 2015). "Higher levels of CRP and leptin were shown to be associated with increased metabolic syndrome components." (PMID 25994228, 2015). "As we all know, hypertension is an important component of metabolism syndrome, which has been proved to associate with many adipokines including adiponectin, leptin, angiotensin, perivascular relaxation factors, and resistin." (PMID 24665369, 2014).
metabolic syndrome (continued). "Genes of interest in this regard are those that show a significant perturbation in expression associated with metabolic syndrome, which is exacerbated by maternal undernutrition and rescued by postnatal leptin treatment." (PMID 24447410, 2014). "These are the genes most strongly associated with the induction of metabolic syndrome by maternal undernutrition and its subsequent rescue by leptin treatment." (PMID 24447410, 2014). "Which of the genes affected by the leptin reversal were associated with the metabolic syndrome seen in UN/Sal/HF offspring." (PMID 24447410, 2014). "Lepob/ob;Fto−/− mice showed an improvement in analysed hallmarks of the metabolic syndrome in comparison to leptin-deficient mice wild type or heterozygous for Fto." (PMID 25144618, 2014). "Weight loss also reduced parameters associated with metabolic syndrome including hyperinsulinemia and the leptin:adiponectin ratio." (PMID 25072025, 2014). "The dyslipidemia and adiposity in the Crh−120/+ mice were associated with significantly elevated plasma leptin concentrations, at 8, 12, and 16 weeks of age in male and female Crh−120/+ after a 4-hour fast." (PMID 24302625, 2014). "The results of our study show that leptin is associated with general and abdominal obesity, dyslipidemia, and IR." (PMID 24981337, 2014). "Leptin remained independently associated with metabolic syndrome risk after additional adjustment for adiposity, cytokines, and CRP." (PMID 24455217, 2013). "But the ratio of adiponectin/leptin decreased progressively with the increase in the number of risk factors for metabolic syndrome." (PMID 23533722, 2013). "Multivariate logistic regression was used to determine the association between leptin and metabolic syndrome (defined per NCEP ATP III) incidence after 6 years of follow-up among 1,120 men and women." (PMID 24455217, 2013). "This study investigates the prospective association between leptin and metabolic syndrome risk in relation to adiposity and cytokines." (PMID 24455217, 2013). "The Kruskal-Wallis rank test was carried out for comparisons of mean rank adiponectin/leptin ratios as a function of a number of risk factors for metabolic syndrome." (PMID 23533722, 2013). "These proteins are secreted by adipose tissue, with high leptin concentrations (leptin resistance) and low adiponectin being both associated with the metabolic syndrome." (PMID 23840881, 2013). "When the analysis was further adjusted for adiposity measures in model 2 and cytokines and CRP in model 3 there was some attenuation in the association between leptin and the risk of metabolic syndrome, but the results remained significant." (PMID 24455217, 2013). "Among women, leptin was significantly associated with the risk of metabolic syndrome at year 6 in both BMI groups after adjusting for potential confounders." (PMID 24455217, 2013). "Women in quintiles 2, 3, 4, and 5 of leptin were at significantly higher risk of developing metabolic syndrome at year 6 as compared to those in quintile 1 after adjusting for potential confounders." (PMID 24455217, 2013). "For both men and women, the incidence of metabolic syndrome was significantly associated with leptin as a continuous variable (P for trend 0.0076 and 0.0003, resp)." (PMID 24455217, 2013). "The risk of metabolic syndrome and serum leptin was linearly associated in models 1 (P = 0.0001), 2 (P = 0.0024), and 3 (P = 0.0098)." (PMID 24455217, 2013). "Since with age body fat is expected to increase in a period of 6 years, therefore, we tested the association between baseline leptin and incidence of metabolic syndrome controlling for adiposity at baseline and also at the 6-year period." (PMID 24455217, 2013). "In recent studies, a single, central administration of recombinant adeno-associated virus vector encoding the leptin gene severely depletes fat and ameliorates the major symptoms of metabolic syndrome for extended periods in rodents." (PMID 23579596, 2013).
metabolic syndrome (continued). "Short sleep duration has been suggested to associate with an increase risk of metabolic syndrome through an upregulation of the neuroendocrine control of appetite, in particular, reduced leptin and increased ghrelin levels." (PMID 22898005, 2012). "The associations between CRP and/or leptin levels and cardiovascular risk factors and metabolic syndrome were determined using independent two sample t-tests to detect gender differences and chi-square tests to evaluate differences in frequencies." (PMID 22533665, 2012). "Upon additional adjustment for BMI, the association between elevated leptin levels with metabolic syndrome score remained in both male (P < 0.001) and female (P = 0.002) subjects." (PMID 22533665, 2012). "The objective of the present study was to determine if CRP and leptin levels are associated with cardiovascular disease risk factors as well as metabolic syndrome score in healthy Taiwanese adults." (PMID 22533665, 2012). "Further studies are necessary to determine if adipose inflammation alters the association of CRP and leptin with metabolic syndrome in obese individuals." (PMID 22533665, 2012). "With the exception of fasting plasma glucose, increased leptin levels were observed as factors associated with metabolic syndrome increased in both males and females." (PMID 21526991, 2011). "Firstly, the retrospective nature of the study prevents determining the direction of causality for the relationship between leptin and metabolic syndrome." (PMID 21526991, 2011). "Leptin levels were measured in adult participants undergoing a routine physical examination, and their relationship with metabolic syndrome as well as CVD risk was assessed." (PMID 21526991, 2011). "After further adjustment for BMI, metabolic syndrome risk remained significantly increased with increasing leptin quartiles in men." (PMID 21526991, 2011). "After adjusting for age, BMI, and tobacco usage, leptin levels were positively associated with metabolic syndrome in females." (PMID 21526991, 2011). "Conversely, the secretion of leptin and adiponectin was used as a predictor to assess the potential risk of developing metabolic syndrome in newborns." (PMID 22050967, 2011). "After adjusting for age alone or with tobacco use, subjects in the highest leptin quartile had a higher risk of having metabolic syndrome than those in the lowest quartile (OR = 6.14 and 2.94 for men and women, respectively)." (PMID 21526991, 2011). "In the Cyprus Metabolism Prospective Cohort Study, leptin as well as its soluble receptor was not only associated with baseline adiposity and metabolic risk factors, but also predicted adiposity, metabolic syndrome, and glucose levels in eighteen-year-old men." (PMID 21526991, 2011). "In the present study, serum leptin levels were associated with metabolic syndrome as well as cardiovascular risk in an adult Taiwanese population." (PMID 21526991, 2011). "In contrast to acute, chronic elevation of plasma leptin to the level observed in patients with the metabolic syndrome impairs renal Na+ excretion, which is associated with the increase in renal Na+,K+-ATPase activity." (PMID 21286276, 2010). "A number of clinical states exhibit evidence of leptin insufficiency, either leptin deficiency or resistance, and they all have in common the metabolic syndrome." (PMID 15530168, 2004). "In obese women with metabolic syndrome, authors identified a lower concentration of the anti‐inflammatory adiponectin, whereas in obese men, the presence of metabolic syndrome is associated with higher circulating leptin and IL‐6 concentrations and increased PBMC cytokine production capacity." (PMID 41489606, 2026). "Metabolic syndrome status also modified leptin effects on MASLD risk." (PMID 40956476, 2025). "Additionally, leptin levels are associated with metabolic syndrome and a higher body mass index (BMI), reflecting the involvement of adipose tissue in inflammatory processes and endothelial damage." (PMID 40283183, 2025).
metabolic syndrome (continued). "Unexpectedly, a longer total breast-feeding duration was associated with a higher risk of being in the “inflammation” (1.04 [1.01;1.07]), “dyslipidemia/high leptin” (1.07 [1.03;1.11]) as well as “low leptin/IGF-1/HbA1c” status (1.06 [1.02;1.11]) as compared to the “normal” status." (PMID 39899498, 2025). "Similarly, serum leptin levels are associated with cardiovascular risk and metabolic syndrome, specifically in individuals with high leptin levels." (PMID 40095937, 2025). "However, this study did not evaluate other major pathological factors associated with lifestyle-related diseases and metabolic syndrome, such as leptin, TNF-α, or interleukin-6." (PMID 40050880, 2025). "As restoring the circulating leptin level to 10% of normal levels is sufficient to alleviate the metabolic syndromes associated with congenital leptin deficiency, the dose of V7-LEP via SQ administration could be further reduced." (PMID 40709262, 2025). "This review proposes that leptin resistance, a hallmark of metabolic syndrome and chronic inflammation, may play a central role in FS pathogenesis by impairing macrophage polarization, perpetuating inflammation, and disrupting fibrosis resolution." (PMID 40095902, 2025). "In addition, visceral adipose tissue produces adipocytokines such as leptin which implicated in the metabolic syndrome." (PMID 40379890, 2025). "Similarly, a cross-sectional study conducted in Karnataka, India, with 88 industrial workers found that night-shift work was significantly associated with elevated leptin levels and a higher prevalence of metabolic syndrome." (PMID 41439942, 2025). "According to investigators, the metabolic syndrome, which includes dyslipidemia as one of its symptoms, may raise the risk of breast cancer by elevating leptin and lowering adiponectin levels in the blood." (PMID 38311739, 2024). "Leptin is suggested to be an independent predictor of future cardiovascular events, and patients with lower adiponectin levels are at risk of coronary heart disease, type 2 diabetes, hypertension, and dyslipidemia." (PMID 38737668, 2024). "The elevated level of leptin SR was linked to dyslipidemia specifically TG level." (PMID 36950695, 2023). "Likewise, the homozygous LEP − 2548AA genotype was observed as a risk factor for the development of dyslipidemia, as well as the heterozygous LEP − 2548GA genotype as a protective factor for DM in the Mexican population." (PMID 37978555, 2023). "Furthermore, psychopharmacological treatment has been found to affect ghrelin and leptin levels in patients with schizophrenia, potentially increasing cardiovascular risk in those with metabolic syndrome." (PMID 37623307, 2023). "So far, it is unknown how protein-rich, low glycaemic meal replacements affect leptin levels in overweight or obese females and males with risk factors of the metabolic syndrome." (PMID 35745267, 2022). "Also, leptin upregulates proinflammatory cytokines such as interleukin 6, which is associated with dyslipidemias, IR, and type 2 diabetes." (PMID 35386232, 2022). "Moreover, it was suggested that novel hepatokine angiopoietin-like protein 8 is as factor that interact with leptin and protect cardiac remodeling among youths with risk for metabolic syndrome by modulation of plasma TG concentration." (PMID 36230994, 2022). "The leptin regulation model used in this research may be further be useful to understand the regulation dynamics in different symptoms such as leptin congenital deficiency, Alzheimer’s disease, and metabolic syndrome." (PMID 35480480, 2022). "However, it has been demonstrated that the adiponectin/leptin ratio (A/L) is more strongly correlated with insulin resistance, metabolic syndrome, carotid intima-media thickness, and an “at-risk phenotype” than individual hormones." (PMID 36558441, 2022).